MAT2A (methionine adenosyltransferase 2A)
Diseases named in the same sentence as MAT2A in open-access papers (continued):
Sharing a sentence is not in itself a finding about the gene and the disease.
injury (1 paper, 2025). Damage inflicted on the body as the direct or indirect result of an external force, with or without disruption of structural continuity. "For instance, in a Phase I trial, the MAT2A inhibitor AG-270 demonstrated dose-limiting toxicity under high-dose exposure, including thrombocytopenia and acute liver injury." (PMID 41236698, 2025).
intervertebral disc degeneration (1 paper, 2023). "Degradation of MAT2A pre-mRNA mediated by METTL16 was disrupted by oxidative stress, which consequently aggravated the apoptosis of nucleus pulposus cells and exacerbated the process of intervertebral disc degeneration." (PMID 37647025, 2023).
kidney cancer (1 paper, 2014). Primary or metastatic malignant neoplasm involving the kidney. "In order to understand the potential mechanism of MAT2A, we further measure the expressions of two kidney cancer related genes COX-2 and HO-1 in RCC patients and cell lines." (PMID 24636201, 2014).
latent infection (1 paper, 2021). "Here, we performed a sub-pooled CRISPR library knockout screen targeting 1773 metabolic-related genes in a cell model of HIV-1 latent infection and found that Methionine Adenosyltransferase 2A (MAT2A) contributes to HIV-1 latency." (PMID 34616406, 2021).
memory impairment (1 paper, 2022). "Artificial knockdown of METTL16 in the hippocampi has been found to result in synaptic disorders and memory impairments by inhibiting the stability of MAT2A mRNA." (PMID 36307396, 2022).
metabolic syndrome (1 paper, 2025). A cluster of metabolic risk factors for CARDIOVASCULAR DISEASES and TYPE 2 DIABETES MELLITUS. "The downregulation of Mat2a in injured PTCs compared with other PTC subclusters supports a model whereby dysregulation of methionine metabolism and subsequent reduction in SAM production in PTCs in the setting of HFD/metabolic syndrome are associated with the emergence of injured cells." (PMID 41031893, 2025).
metastatic diseases (1 paper, 2021). "We believe our findings will encourage future clinical trials examining MAT2A inhibitors in MTAP-deleted NPC, including recurrent and metastatic diseases, which are often deadly." (PMID 34234122, 2021).
myeloma (1 paper, 2021). "Importantly, we found that some of the genes (i.e., MAT2A, AHCY, MTR and MTAP) were upregulated in MGUS and smouldering myeloma patients as compared to healthy individuals." (PMID 33579905, 2021).
non-small cell lung carcinoma (1 paper, 2025). A group of at least three distinct histological types of lung cancer, including non-small cell squamous cell carcinoma, adenocarcinoma, and large cell carcinoma. "Inhibiting MAT2A has been used to sensitize chemotherapy-resistant cells, reducing migration and proliferation and increasing apoptosis of non-small cell lung cancer due to changes in histone methylation." (PMID 39941901, 2025). "The combination of METTL3, which is increased in non-small cell lung cancer, and MAT2A inhibitions is able to decrease m6A mRNA modification, leading to apoptosis." (PMID 39941901, 2025).
Obesity (1 paper, 2022). Accumulation of substantial excess body fat. "Obesity did not affect the expression of Bhmt, Mtr and Mat2a." (PMID 35198059, 2022).
osteoporosis (1 paper, 2025). A condition of reduced bone mass, with decreased cortical thickness and a decrease in the number and size of the trabeculae of cancellous bone (but normal chemical composition), resulting in increased fracture incidence. "Our study also verified that GTF2I affected osteoporosis in mice through the miR‐134‐5p/MAT2A axis." (PMID 40191097, 2025). "Additionally, its essential role in osteoclastogenesis suggests that MAT2A may offer a promising therapeutic target for osteoporosis related to osteoclast dysfunction." (PMID 40191097, 2025).
periodontitis (1 paper, 2024). An acute or chronic inflammatory process that affects the tissues that surround and support the teeth. "The elevated MAT2A expression in both the inflamed gingival tissues and P. gingivalis-infected GFs indicated that MAT2A-mediated methionine metabolism may participate in the development of periodontitis." (PMID 38130504, 2024). "In the present study, we for the first time reported that methionine metabolism was elevated in the gingival tissues of periodontitis patients, and MAT2A inhibition can reduce SAM generation and inflammatory response in hGFs by inhibiting the NF-κB/MAPK signaling pathway." (PMID 38130504, 2024). "Targeting MAT2A may provide a novel therapeuticmethod for modulating periodontitis." (PMID 38130504, 2024).
progeria (1 paper, 2023). "Notably, the higher levels of ATP, impaired Akt2 signaling, and low pyruvate kinase activity in human senescent and mouse progeria myoblasts were reversed by inhibition of MAT2A, suggesting that increased methionine catabolism might be affecting glycolysis." (PMID 36797255, 2023).
renal fibrosis (1 paper, 2020). A final common manifestation of a wide variety of chronic kidney diseases characterized by glomerulosclerosis and tubulointerstitial fibrosis. "Mir-181a-5p has been found to downregulate lipid metabolism regulator PPARα and is in silico predicted to downregulate MAT2A, TIMP3, and LGSF11; miR-451 downregulates YWHAZ and CAB39, which could be implicated in renal fibrosis and mesangial hypertrophy." (PMID 32849923, 2020).
T-cell leukemia (1 paper, 2020). A malignant disease of the T-lymphocytes in the bone marrow, thymus, and/or blood. "Due to the recent lack of appropriate MAT2A inhibitors, cycloleucine as a substrate-competitive inhibitor with low affinity to MAT2A, has been used to block MAT2A non-specifically in T-cell leukemia and other tumor entities with unclear effects and also affecting other essential pathways." (PMID 32456310, 2020).
vitamin B12 deficiency (1 paper, 2014). A disease characterized by low serum levels of vitamin B12, either inherited or acquired. "The MAT2a mRNA levels were comparable to control in the vitamin B12 deficiency in the presence of normal folic acid levels (NFBD)." (PMID 25003120, 2014). "In the group with vitamin B12 deficiency in the presence of excess folic acid levels (condition for “methyl trap”), there was a reduction of MTHFR and MTR mRNA levels but increase in levels of MAT2a, PEMT, and CBS mRNA levels." (PMID 25003120, 2014).
cancer (84 papers, 2008 to 2026). A tumor composed of atypical neoplastic, often pleomorphic cells that invade other tissues. "MAT2A was found as a synthetic lethal target in methylthioadenosine phosphorylase (MTAP)‐deficient cancer cells, and the mechanism involves SAM‐utilizing protein arginine methyltransferase 5 (PRMT5)." (PMID 39309689, 2024). "The interaction between MTAP loss and codeletions in MAT2a or PRMT5 is characterized as synthetic lethal in cancers." (PMID 38000655, 2024). "MAT2A is associated with cancer cell growth and proliferation, and dysregulation of MATs is associated with activation of LIHC." (PMID 37240447, 2023). "The previous studies display that MAT2A is associated with uncontrolled cell proliferation in cancer." (PMID 28316886, 2017). "Therefore, MAT2A inhibitors have the potential to be used as therapeutic candidates for MTAP deficient cancers." (PMID 40240755, 2025). "Additionally, AG-270 induces DNA damage and impairs DNA repair activity in MTAP-deficient cells, suggesting that MAT2A inhibition could enhance the efficacy of cancer therapies targeting DNA damage responses." (PMID 40430461, 2025). "In future studies it will be necessary to continue to reveal the biological characteristics of MAT2A function for further exploring the potential of MAT2A-targeted cancer therapies." (PMID 41445748, 2025). "There is added credence to MAT2A as a bona fide drug target, as inhibitors of MAT2A are being investigated in Phase I clinical trials for tumors with loss of the gene MTAP, constituting 15% of cancers." (PMID 40880532, 2025). "As one of the three methionine adenosyltransferase (MAT) isoforms, MAT2A is predominantly expressed in extrahepatic tissues and cancer cells, where it supports tumor growth by driving transcriptional and metabolic reprogramming." (PMID 40430308, 2025). "Inhibition of MAT2A by shRNA or inhibitors has reduces the proliferation of several cancer cell lines through inducing the global depletion of H3K36me3, and MAT2A knockdown prolonged the median survival in DIPG13p model mice." (PMID 41445748, 2025). "Abnormal methionine cycle has been observed in lung cancer, showing a metabolic dependence of methionine in cancer stem cells, correlating with high MAT2A expression and transmethylation rates." (PMID 39941901, 2025). "The overexpression of MAT2A has been observed in various human cancers, including lung cancer, gastric cancer, liver cancer, and leukemia, to meet the biosynthetic demands associated with RNA m6A hypermethylation." (PMID 40295500, 2025). "Recent studies have demonstrated that the inhibition of MAT2A results in a selective antiproliferative effect in cancers characterized by MTAP deletion." (PMID 40590219, 2025). "In conclusion, targeting methionine metabolism via MAT2a or AHCY inhibition is a possible avenue to arrest cancer progression and improve outcomes for GBM patients." (PMID 40015640, 2025). "Either way, the effectiveness of PRMT5 and MAT2A inhibitors depends on the accumulation of MTA in cancer cells with MTAP gene deletion." (PMID 41465382, 2025). "While MAT2A inhibition in these cancers represents an alternative strategy, poor pharmacokinetics and cellular adaptation induction blunt their utility." (PMID 40590219, 2025). "A number of studies have found that expression of MATs is higher in various cancer tissues than that in normal tissues, and the inhibitors of methionine adenosyltransferase MAT2A receive extensive attention in the cancer therapy." (PMID 41445748, 2025). "It is an oral, reversible, highly potent and selective MAT2A inhibitor that has been shown to be active against MTAP-deleted cancer cells in cell cultures and animal models." (PMID 41465382, 2025).
cancer (continued). "In this context, MAT2A inhibition has been shown to suppress MTAP‐deleted cancers via a synthetic lethality mechanism that involves further reduced PRMT5 activity." (PMID 40552664, 2025). "MAT2A inhibitors efficiently suppress the activity of MAT2A, leading to a substantial decline in SAM levels and exhibiting robust anti-proliferative effects through synthetic lethality in MTAP-deficient cancer cells." (PMID 40430461, 2025). "In cancer cells, an increase in MAT2A expression is observed, which weakens the inhibitory effect of MTA on PRMT5 and slightly increases the histone methylation process in cells with MTAP deletion." (PMID 41465382, 2025). "Genetic knockdown screening libraries revealed that in the 15% of cancers with MTAP loss, enhanced dependence is conferred on methylthioadenosine transferase 2 alpha (MAT2a, EC:2.5.1.6) and protein arginine methyltransferase 5 (PRMT5, EC:2.1.1.320)." (PMID 38000655, 2024). "Mouse studies here predict efficacy as an anticancer agent in combination with MAT2a inhibitors for cancers of MTAP+/+ and MTAP−/− genotypes." (PMID 38000655, 2024). "The metabolic enzyme methionine adenosyltransferase 2A (MAT2A) was found to elicit synthetic lethality in methylthioadenosine phosphorylase (MTAP)‐deleted cancers, which occur in about 15% of all cancers." (PMID 39309689, 2024). "The drug synergy afforded by combination MTDIA and AG-270 treatment suggests that MTDIA has the potential to expand the use of MAT2a inhibitors to CRCs and other cancers that are MTAP+/+." (PMID 38000655, 2024). "In MTAP−/− cancer cell lines, MAT2a inhibitor AG-270 has a reported IC50 of 260 nM for growth inhibition." (PMID 38000655, 2024). "This work investigates the potential of MTDIA to induce the MTAP−/− synthetic lethal phenotype in MTAP+/+ cancers when combined with MAT2a inhibitors." (PMID 38000655, 2024). "Since MTAP‐deletion occurs at high frequency in almost 15% of all human cancer types, the synthetic lethality emerges MAT2A as a potential target for cancer treatment." (PMID 39309689, 2024). "Treatment with FIDAS, a small molecular inhibitor of MAT2A, inhibit the expression of MAT2A mediated cancer stem cell marker and histone methylated marker in MB49-CR cells and decreased the cell viability of MB49-CR cells with cisplatin treatment." (PMID 37582769, 2023). "Studies show that methionine adenosyltransferase 2A (MAT2A) inhibitors induce synthetic lethality of MTAP-deleted cancer, especially in combination with taxanes and gemcitabine, which demonstrate a potential to treat MPM of the nuclear DAMPs subtype." (PMID 37033966, 2023). "We further validated MAT2A and cancer stem cell markers were up-regulated and circARHGAP10 was down-regulated through the regulation of MAT2A protein stability in cisplatin resistant BCa cells." (PMID 37582769, 2023). "Increased MAT2A expression has also been found in various cancers, including those of the liver and breast." (PMID 37240447, 2023). "PRMT5 ablation alone also recapitulates FA pathway deficiency seen in MTAP-deleted tumors, mimicked by the use of MAT2A inhibitors in MTAP-deleted cancers that was found to be synergistic with docetaxel in squamous lung and pancreatic PDX models." (PMID 37861290, 2023). "MAT2A contributes to tumour progression in multiple types of cancers by promoting methionine metabolism." (PMID 36371321, 2022). "The growth of MTAP-deleted cancer cells is blocked as a result of MAT2A inhibition which lowers PRMT5-dependent mRNA splicing and prompts DNA damage." (PMID 36572880, 2022). "In agreement with previous findings, we also found that the survival period of patients with different cancers displaying high MAT2A expression level became significantly shorter by analyzing overall survival." (PMID 35729157, 2022). "AG-270 is a safe, tolerable and first-in-class oral MAT2A inhibitor that reduces the proliferation of cancer cells and tumors that lack MTAP." (PMID 36572880, 2022).
cancer (continued). "For example, co-deletion of genes near p16 including MTAP and several interferons is common in several cancers, and subsequently all these drivers paired with MAT2A as the SL partner." (PMID 36517508, 2022). "A Met-restricted diet or treatment with an MAT2A inhibitor is a potential way to treat cancer by the targeted elimination of the cancer stem cell population." (PMID 36429035, 2022). "It will now be important to investigate METTL16 function in MAT2A regulation in pluripotent stem cells and cancer models, as these cell types have an unusually high dependence on methionine, and altered metabolism is a hallmark of cancer." (PMID 36553579, 2022). "More recent studies have identified MAT2A as a viable target in MTAP-deleted cancers, and clinical development has begun for the MAT2A inhibitor, AG-270." (PMID 35804819, 2022). "Reduced lysine acetylation at MAT2A residue 81 promoted cell proliferation in HCC, while MAT2A sumoylation protected cancer cells against 5-fluorouracil (5-FU) induced apoptosis." (PMID 36371321, 2022). "Methionine cycle enzymes have been found to be enriched in numerous tumor types, and MAT2A expression impinges upon the sensitivity of certain cancer cells to therapeutic inhibition." (PMID 34065390, 2021). "The MAT2A inhibitor AG-270 applied to MTAP−/− cancer cells inhibits SAM production, together with increased MTA resulting in decreased SDMA levels as its mechanism of action." (PMID 33893330, 2021). "Along similar observations, the inhibition of the methionine cycle rate-limiting enzyme, methionine adenosyltransferase 2A (MAT2A), which led to a block in methionine utilization, was useful in preventing cancer relapse." (PMID 33804114, 2021). "Methionine depletion induced MAT2A mRNA and protein that sensitized cancer stem cells to MAT2A inhibition by siRNAs or cycloleucine." (PMID 34065390, 2021). "The significant investigation into the design of PRMT5 and MAT2A inhibitors in recent years makes the possibility of co-inhibition of MTAP a new possibility for MTAP+/+cancers as well as its use as a monotherapy." (PMID 33893330, 2021). "Current efforts toward MAT2A inhibitor development are focused towards treating MTAP−/− cancers, with agent AG-270 in clinical trials enrolling patients with MTAP-deleted solid tumors (NCT03435250)." (PMID 33893330, 2021). "To generally elucidate the impact of MAT2A in cancer, we mined the literature and compared the expression level of MAT2A in different patient cancer entities." (PMID 32456310, 2020). "MAT2A overexpression enhances cancer cell growth and survival, as there is a positive feedforward loop between MAT2A and polyamines and MAT2A protein positively regulates B-Cell CLL/lymphoma 2 (BCL-2) expression." (PMID 29108270, 2017). "Immunohistochemical analysis and western blotting indicated that level of MAT2A protein was decreased in cancer tissues." (PMID 24636201, 2014). "Analysis of mRNA levels reveals 19/24 (79.2%) of RCC patients have reduced MAT2A mRNA level in cancer tissues." (PMID 24636201, 2014). "The western blotting analysis showed similar trend with immunohistochemical result in that protein content of MAT2A was less in cancer tissues relative to adjacent normal tissues." (PMID 24636201, 2014). "In our study, the content of MAT2A is obviously decreased in cancer tissue of RCC patients under mRNA and protein levels." (PMID 24636201, 2014). "Our results suggest that MAT2A is downregulated in cancer tissues of RCC patients and has function of tumor suppressor though repressing the expression of heme oxygenase-1 (HO-1)." (PMID 24636201, 2014). "MAT2A transcript was significantly downregulated in cancer tissues compared to normal tissues (P < 0.05)." (PMID 24636201, 2014). "The immunohistochemical examinations indicated that MAT2A protein is mainly present in nuclei and level of it was obviously downregulated in cancer tissues compared to adjacent normal tissues." (PMID 24636201, 2014).